ABCG2 (ATP binding cassette subfamily G member 2 (JR blood group))
Diseases named in the same sentence as ABCG2 in open-access papers (continued):
Sharing a sentence is not in itself a finding about the gene and the disease.
cancer (continued). "RuZ has a high drug loading rate, and this, in combination with its typical octahedral structure, decreases its interaction with the ABCG2 and ABCB1 transporters, producing an increase in RuZ retention in drug-resistant cancer cells." (PMID 37408573, 2023). "As an ABC transporter, endogenous ABCG2 expression in certain cancers is likely a reflection of the differentiated phenotype of the cell of origin and likely contributes to intrinsic drug resistance." (PMID 37919637, 2023). "ATP-binding cassette transporters, including ABCB1 (P-glycoprotein) and ABCG2 (BCRP/MXR/ABCP), are pivotal in multidrug resistance (MDR) development in cancer patients undergoing conventional chemotherapy." (PMID 37762275, 2023). "P-glycoprotein (ABCB1), ABC efflux transporter protein MRP1 (ABCC1), and breast cancer resistance protein (BCRP) (ABCG2), among other drug efflux transporters, have been identified as important mediators of MDR in cancer cells." (PMID 37104009, 2023). "Drug efflux pumps, such as ABC transporters, ABCG2 or ABCB1, are activated in SP cells and help to efflux various cancer drugs, thereby generating a multidrug resistance phenotype." (PMID 36605488, 2023). "Expression levels of the EMT marker c-MET, cancer stemness markers ABCG2 and CD133a, which is both HH-GLI target and cancer stemness marker, were significantly decreased in the combined treatment of 5-FU and ATO." (PMID 36900263, 2023). "Additionally, ABCG2-positive cells were positioned mainly in the front of carcinomatous tissue or between the carcinomatous and non-carcinomatous margin tissue, which supports the hypothesis that ABCG2 plays an essential role in cancer progression." (PMID 37445716, 2023). "Side-population (SP) analysis is a widely used assay for isolating cancer cells with the ability to efflux DNA-binding fluorescent dyes via the ATP-binding cassette (ABC) transporters, such as BCRP/ABCG2 and MDR1/ABCB1." (PMID 36676146, 2023). "The intracellular concentration of HS-173 was considerably lower in ABCB1-overexpressing NCI-ADR-RES and ABCG2-overexpressing S1-MI-80 cancer cells as compared to the parental OVCAR-8 and S1 cancer cells." (PMID 37048130, 2023). "Additional markers such as CD151, CD147, and drug transporter proteins (ABCG2/CD338), (MDR1/ABCB1/CD243) have been reported to interact and co-express with CD44 on cancer cells." (PMID 36834918, 2023). "Among them, three subfamilies commonly involved in cancer MDR are P-glycoprotein (P-gp), multidrug resistance protein 1 (MRP 1 or ABCC1), and breast cancer resistance protein (BCRP or ABCG2)." (PMID 37760764, 2023). "Targeting c-MET activity, either with small molecule inhibitors or RNA interference, has been shown to suppress the cancer stem-like phenotype by downregulating CSC markers, including CD133, CD44, ABCG2, Sox2, and ALDH1." (PMID 38201226, 2023). "Researchers propose repurposing existing drugs to sensitize multidrug-resistant cancer cells, which overexpress ABCB1 or ABCG2, to conventional anticancer drugs." (PMID 37762275, 2023). "The overexpression of P-gp, ABCG2, and ABCC1 is one of the major impediments to successful chemotherapy for cancer patients." (PMID 37444569, 2023). "However, three of these transporters are expressed in cancer cells and specifically have been associated with MDR: P-glycoprotein (P-gp or ABCB1), multidrug resistance-associated protein 1 (MRP1 or ABCC1), and the breast cancer resistance protein (BCRP or ABCG2)." (PMID 36678870, 2023). "It has the capability to sensitize multidrug-resistant cancer cells that overexpress ABCB1 and ABCG2 to cytotoxic anticancer drugs by attenuating their drug efflux function." (PMID 37762275, 2023). "Treatment with tariquidar or Ko143 was able to restore the activity of HS-173 to induce cell apoptosis in KB-V1 and S1-MI-80 cancer cells by inhibiting the drug transport function of ABCB1 and ABCG2, respectively." (PMID 37048130, 2023).
cancer (continued). "ABCG2 and MRP1, as the proteins of the ATP-binding cassette (ABC) transporter family, participate in the process of cancer cell chemotherapy resistance." (PMID 37489008, 2023). "For this purpose, the impact of imperatorin on the protein expression of ABCG2 was investigated in S1-MI-80 and H460-MX20 cancer cells." (PMID 38004460, 2023). "Gene expression analysis showed that the levels of cancer stem cell and EMT markers ABCG2, CD133 and c-MET significantly increased after chemotherapy treatment and were impaired by HH-GLI inhibition and the combination of 5-FU and GANT61." (PMID 36900263, 2023). "As the first step in this study, we determined the cytotoxicity of HS-173 in multiple paired parental cancer cell lines and respective sublines expressing either ABCB1 or ABCG2." (PMID 37048130, 2023). "Increased ABC transporter expression, including ABCB1 (P-glycoprotein/MDR1), ABCC1 (MRP1), and ABCG2 (BCRP), is one of the most well-established strategies for cancer cells to acquire multidrug resistance (MDR)." (PMID 36902427, 2023). "A multitude of natural products have demonstrated the ability to reverse MDR in cancer cells that overexpress ABCB1 and ABCG2." (PMID 38004460, 2023). "To further investigate the importance of ABC proteins and their engagement in different cancer-related processes, in this manuscript, we decided to compare two CRC subgroups presenting high expression levels of two ABC members: ABCC4 and ABCG2." (PMID 38067326, 2023). "For further biological investigations, we have used cancer cell lines with different amounts of ABCB1 and ABCG2 expression levels." (PMID 38004447, 2023). "Studies also prove that CD338+/ABCG2+ cells have an adaptive advantage in vivo over the differentiated bulk of cancer cells, and notably both ABCG2+ and ABCG2− cell subpopulations were observed to display similar tumorigenic potential." (PMID 36834918, 2023). "To explore the role of TOX3/ABCG2 signaling axis in CRC, we firstly investigated the function of TOX3 itself in cancer development." (PMID 37708089, 2023). "A predominant approach for a modulator to overcome MDR mediated by ABCB1 and ABCG2 involves directly impeding the activity of ABCB1 and ABCG2 within multidrug-resistant cancer cells." (PMID 37762275, 2023). "Among the selected cancer stemness genes, we found that TERT, MYC, CD44, BMI1, ABCB1 and ABCG2 were highly expressed in OCM1 cells compared to their expression in C918 cells, whereas the expression of ZEB1 was opposite to that of the stemness genes." (PMID 35404029, 2022). "To determine the effects of ABCG2 on cancer in humans, we used TIMER2.0 to explore ABCG2 expression in various types of cancer from the TCGA database." (PMID 36555598, 2022). "Secondly, because cancer SP cells highly express three ATP-binding cassette (ABC) transporters, ABCB1 (also known as MDR1/P-glycoprotein), ABCC1, and ABCG2 (also known as BCRP), they are thought to be chemo-resistant tumor-initiating cells." (PMID 35659728, 2022). "Inhibition with PFK158 or genetic knockdown of PFKFB3 showed reduced tumor formation in the CSC xenograft model with reduced expression of phospho-PFKFB3 S461 and total PFKFB3, and cancer stem cell markers including CD133, CD44, Aldh1, Sox2, and ABCG2." (PMID 35804016, 2022). "Cancer cells are known to develop chemoresistance through upregulation of ABCB1 and ABCG2 expression, preventing chemotherapy from reaching the target tissue." (PMID 35209919, 2022). "More importantly, we found that hydroxygenkwanin and Ko143 significantly restored the intracellular accumulation of PhA in ABCG2-overexpressing NCI-H460/MX20 and A549-Bec150 cancer cells, as well as in ABCG2-transfected R482-HEK293 cells." (PMID 36361555, 2022). "Currently, it is recognized that the main role in multi-drug resistance of cancer cells in vitro is played by ABCB1 (P-gp), ABCC1 (MRP1), ABCC2 (MRP2), ABCC4 (MRP4), ABCG2 (BCRP) and lung resistance protein (LRP)." (PMID 36613834, 2022).
cancer (continued). "The overexpression of ATP-binding cassette transporter G2 (ABCG2), also known as breast cancer resistance protein (BCRP), can make cancer cells resistant to chemotherapeutic drugs such as mitoxantrone and doxorubicin with ABCG2 as the substrate." (PMID 35959356, 2022). "For the non-cancer HFFF2 cells, a decrease in the level of all mRNA tested, FECH but also PPOX and ABCG2, was indeed observed following combination of all treatments." (PMID 35886979, 2022). "CCL2, CRIM1, COL1A1, 6A1, 6A2 participate in cell migration, invasion, or EMT and ABCG2, ALDH1A1, NES are cancer stem‐cell markers." (PMID 36305167, 2022). "Specifically, some ABC transporters, such as ABCC1, ABCG2, and ABCB1, are highly efficient at extruding drugs from cancer cells, resulting in substantial multidrug resistance." (PMID 35280774, 2022). "Several members of the ABC family, such as ABCB1, ABCC2, and ABCG2, have been shown to contribute to the development of MDR in a variety of cancers." (PMID 36059609, 2022). "ABCG2 also contributes to EMT and cancer metastasis, and is a direct target of TGF-β1 in tumor cells." (PMID 35684095, 2022). "The expression of ABC transporter family members such as MDR-1, ABCG2, MRP1, and MRP3 has been documented in several cancers, including GBM." (PMID 36012307, 2022). "In many kinds of human tumor cells, ABCG2 expression on the plasma membrane contributes to MDR during chemotherapy, and ABCG2 is also known to be a marker for identifying cancer stem cells (CSCs) in lung cancers." (PMID 35190588, 2022). "The inhibition of ABCG2 can affect the ADMET characteristics of drugs, which was also considered as a promising strategy to enhance the efficiency of chemotherapy in cancer treatment." (PMID 35665065, 2022). "G‐CSF increases a cancer stem cell phenotype through upregulation of octamer‐binding transcription factor 3/4 (Oct3/4), nanog homeobox pseudogene 8 (NANOGP8), and ATP‐binding cassette transporter G2 (ABCG2)." (PMID 35612789, 2022). "The data demonstrated that the treatment of drug-resistant S1-M1-80 cancer cells and ABCG2 transfected HEK293/R2 cells with 6 μM of VKNG-1 for 72 h notably diminish the ABCG2 protein expression in comparison with the vehicle." (PMID 34572902, 2021). "Most prominent and well-studied are ABCB1, ABCC1, and ABCG2, not only due to their contribution to the multidrug resistance (MDR) phenotype in cancer, but also due to their contribution to AD." (PMID 34977908, 2021). "The incubation of drug selective S1-M1-80 cancer cells and ABCG2 transfected HEK293/R2 cells with 6 μM of VKNG-1 for 72 h remarkably decreased the ABCG2 protein expression compared to cells incubated with vehicle." (PMID 34572902, 2021). "The overexpression of ATP-binding cassette transporter, ABCG2, plays an important role in mediating multidrug resistance (MDR) in certain types of cancer cells." (PMID 33671108, 2021). "Furthermore, ABCG2 overexpression could confer resistance to OTS964 in cancer cells." (PMID 33658942, 2021). "In conclusion, PFC is a novel inhibitor of ABCG2 and has promise as a therapeutic to overcome ABCG2-mediated MDR, to improve the efficiency of cancer chemotherapy." (PMID 34830383, 2021). "Pgp and/or some other drug transporting ABC proteins (e.g., ABCG2, MRP1) are overexpressed in nearly all cancers and cancer stem cells by which cancer cells become resistant against many drugs." (PMID 34959345, 2021). "Aside from CD133+, which is also found in persister cancer cells, CD24-, CD44+, ABCB1+, ABCG2+ and ALDH+ are common phenotypic markers for CSCs." (PMID 35582031, 2021). "It has been reported that ABC transporter genes such as ABCG2 and ABCB5 often become upregulated in cancers of pancreas, breast, lung, ovary, and skin, and can be the potential targets for therapy." (PMID 34358102, 2021).
cancer (continued). "In contrast, we discovered that TP-3654 significantly resensitized ABCG2-overexpressing S1-M1-80, H460-MX20 cancer cells and ABCG2-transfected R482-HEK293 cells to ABCG2 substrate drugs mitoxantrone, SN-38 and topotecan, in a concentration-dependent manner." (PMID 34502348, 2021). "Efflux transporters (ETs) such as P-glycoprotein (P-gp, ABCB1), multidrug resistance-associated protein (MRP, ABCC), and breast cancer resistance protein (BCRP, ABCG2) actively pump anti-cancer drugs out of cancer cells." (PMID 33800412, 2021). "The ATP-binding cassette transporter ABCG2 mediates the efflux of several chemotherapeutic drugs, contributing to the development of multidrug resistance (MDR) in many cancers." (PMID 33469044, 2021). "In the ABC protein superfamily, human breast cancer resistance protein (BCRP, ABCG2) is the main efflux transporter, and its overexpression in cancer-resistant cell lines leads to MDR31." (PMID 34659526, 2021). "ABCG2, known as breast cancer resistance protein (BCRP), can make cancer cells resistant to a variety of drugs, such as topotecan, mitoxantrone and daunorubicin." (PMID 34677502, 2021). "The development of cancer chemoresistance is upregulated by several ABC transporters including ABCB1, ABCC1, ABCC2, and ABCG2." (PMID 34066059, 2021). "Among them, ABCB1 (P-glycoprotein; P-gp, MDR1), ABCC1 (multidrug resistance-associated protein 1; MRP1), and ABCG2 (breast cancer resistance protein; BCRP, mitoxantrone resistance protein; MXR) are the major transporters involved in MDR, in cancer cells." (PMID 34830383, 2021). "Studies show that overexpression of ABCG2 is responsible in both innate and acquired MDR phenotypes in cancer stem cells." (PMID 34536148, 2021). "In multiple myeloma cells, hypoxia activates EMT program and increases the expression of stem cell transcription factors, ABCG2 and ALDH1 to impart cancer stem cell phenotype and metastasis." (PMID 33968778, 2021). "Among these transporters, ABCB1 (MDR1, P-pg), ABCG2 (BCRP), and ABCC1 (MRP1) are widely investigated in past 20 years which were well-related with MDR in cancer." (PMID 33593355, 2021). "In recent years, more ABC transporters have been identified to be related with MDR in cancer besides ABCB1, ABCG2, and ABCC1." (PMID 33593355, 2021). "Significant changes in tumour angiogenesis, cancer cell proliferation, apoptosis, HIF1α levels, HIF-1 target genes and ABCG2 were found both in vitro and in tumour tissue." (PMID 34546500, 2021). "As it is well-known that drug transporters play a crucial role in cancer drug resistance, we examined the expression levels of several drug transporters, including ABCB1 (MDR1), ABCC1 (MRP1), ABCG2/BCRP, and LRP/MVP, in MDA-MB-231Tx cells by RT-PCR." (PMID 34944868, 2021). "Overexpression of ATP-binding cassette transporter superfamily G member 2 (ABCG2), is known as a major mechanism mediating multidrug resistance (MDR) in cancer cells." (PMID 34336849, 2021). "Previously, a study showed that the activation of the PI3K/AKT pathway increases the ABCG2 protein expression, thereby increasing the likelihood of MDR in certain cancer cells." (PMID 34572902, 2021). "Analysis of TCGA (the Cancer Genome Atlas) datasets suggested that the level of LINC00963 was positively correlated with the expression of the cancer stemness markers (Sox2 and CD44) and drug resistance markers (ABCG2 and ABCB5)." (PMID 32357409, 2020). "High ABCG2 expression was also reported in late stages (stage III and state IV) cancers that showed MDR." (PMID 33364237, 2020). "Considering the intimate connection between EMT and cancer stemness, we further examined the expression of six key biomarkers of cancer stemness (NANOG, SOX2, OCT4, CD44, ABCG2, BMI1)." (PMID 32863941, 2020). "ABCB1, ABCB4, ABCG2, and ABCC2 are well-described markers of drug resistance development in many cancers." (PMID 31991882, 2020).
cancer (continued). "We then analyzed the effect of Lin28A on the proportion of OC cancer stem cell marker CD133+, CD44+, and ABCG2+ cells by flow cytometry." (PMID 32398961, 2020). "ABCB1 expression correlated with ICEC0942 and THZ1 response, and ABCG2 expression with THZ2 response, in a panel of cancer cell lines." (PMID 31530935, 2020). "ABCG2 is a xenobiotic drug efflux pump, which is known to transport SN38 (the active metabolite of irinotecan) out of cancer cells thereby making the cancer cells less sensitive to irinotecan treatment." (PMID 32708825, 2020). "PCSCs express markers of cancer stem cells (CSCs) including CD24, CD133, CD44, and epithelial specific antigen as well as the drug transporter ABCG2 grow as spheroids in a defined growth medium." (PMID 34841087, 2020). "Our data suggest that sitravatinib re-sensitizes ABCB1- and ABCG2-overexpressing multidrug-resistant cancer cells by attenuating the drug transport function of ABCB1 and ABCG2." (PMID 31941029, 2020). "The two ABC transporters most commonly involved with the development of MDR in cancer cells are the ABC transporter subfamily B member 1 (ABCB1/P-gp/MDR1) and the ABC transporter subfamily G member 2 (ABCG2/BCRP/MXR)." (PMID 32098067, 2020). "We demonstrated that by modulating the transport function of both ABCB1 and ABCG2, sitravatinib re-sensitizes ABCB1- and ABCG2-overexpressing multidrug-resistant cancer cells to chemotherapeutic agents." (PMID 31941029, 2020). "We demonstrated that SNX-2112 inhibited cancer cell proliferation, decreased ABCB1 and ABCG2 gene expression levels and reduced the colony formation capacity of ECSLCs, which was enhanced by STAT3 silencing." (PMID 33390934, 2020). "In particular, apatinib was able to prevent multidrug resistance (MDR) of cancer cells against other conventional chemotherapeutic drugs by inhibiting ABCB1 and ABCG2-mediated drug export." (PMID 31399906, 2020). "In conclusion, we reveal a potential drug repositioning treatment option for multidrug-resistant cancers by targeting ABCB1 and ABCG2 with sitravatinib and should be further investigated in future clinical trials." (PMID 31941029, 2020). "In the present study, 5-FUR PDAC cells upregulated their expression of cancer stem cell markers Nanog, Oct4, and CD133, and ABCG2 and displayed higher sphere-formation ability than did control PDAC cells." (PMID 32629871, 2020). "Specifically, ABCB1, ABCG2, and ABCC1 are able to confer cancer cell MDR to a wide range of anticancer drugs with different chemical structures and mechanisms of action." (PMID 33692943, 2020). "In many MDR cancer cells, P-glycoprotein (P-gp, also known as ABCB1 and MDR1) and breast cancer resistance protein (BCRP, also known as ABCG2, ABCP and MXR), two vital ABC members, are overexpressed." (PMID 31952518, 2020). "Two efflux transporters from the ATP-binding cassette (ABC) family, ABCB1 and ABCG2, are thought to contribute to multidrug resistance (MDR) in cancer." (PMID 31729540, 2020). "Most studies investigating DNA methylation of ABC transporters in cancer are limited to ABCB1, ABCC1, and ABCG2, only few studies hint at aberrant DNA methylation of other members of the ABC transporter family." (PMID 33066132, 2020). "Several receptor tyrosine kinase inhibitors (RTKIs) have been reported to interact strongly with ABCB1 and/or ABCG2 and reverse multidrug resistance in cancer cells overexpressing ABCB1 and/or ABCG2." (PMID 32466597, 2020). "Western blot assays showed that the decreased CDH1 expression and enhanced mesenchymal (CDH2 and vimentin) and cancer stemness (CD44, ABCG2, OCT4 and MYC) marker expression were abolished after treating MCF-7OE-UBE2O cells with rapamycin." (PMID 31907353, 2020). "ABCB1, ABCC1, and ABCG2 are ATP-binding cassette (ABC) transporters functioning as efflux pumps, lowering intracellular accumulation of various anti-cancer drugs." (PMID 33066132, 2020).